MIR320D2 (microRNA 320d-2)
Synonyms: hsa-mir-320d-2; formerly MIRN320D2
Gene: MicroRNA gene on chromosome X (140,926,172 to 140,926,219, reverse strand). Ensembl gene ENSG00000221081.
Gene Ontology:
Biological process: cellular response to glucose stimulus; long-term synaptic potentiation; miRNA-mediated post-transcriptional gene silencing; negative regulation of gene expression; positive regulation of stem cell proliferation
Cellular component: RISC complex
Homologues: Orthologues: chimpanzee ptr-mir-320d-3 (100% identical), tropical clawed frog xtr-mir-320 (50% identical). Paralogues in human: MIR320E (92% identical), MIR320A (90% identical), MIR320B1 (85% identical), MIR320C2 (83% identical), MIR320B2 (81% identical).